APOE (apolipoprotein E)
Diseases named in the same sentence as APOE in open-access papers (continued):
Sharing a sentence is not in itself a finding about the gene and the disease.
dementia (continued). "Although the microglial phenotype was insufficient in predicting the APOE status in dementia, the elevated markers of phagocytosis, adaptive immune response and antigen recognition seen in APOE4 carriers point towards a more pathological environment." (PMID 30394574, 2019). "Although a higher HDL-R is associated with higher cognition and a lower probability of dementia, large differences in HDL-R are required to offset the associations attributable to APOE genotype." (PMID 31022959, 2019). "Since apoE is a carrier of plasma cholesterol, it is of interest to determine the contribution of cardiovascular disease pathology to dementia in carriers of different APOE isoforms." (PMID 30890171, 2019). "After exclusion of patients with dementia at baseline, and censoring in the main analysis at time of incident dementia diagnosis, effect estimates for mortality remained similar for APOE-ε2 (HR 0.95, 0.90–1.01), but attenuated for APOE-ε4 (HR 1.07, 1.01–1.12)." (PMID 31356640, 2019). "The effect of the APOE gene on cognition and dementia is also modified by other genetic factors, including the SORL1, PICALM, CR1, ABCA7, TREM2, and BIN1, showing complex gene-gene effects." (PMID 30866553, 2019). "Global volumes and regional patterns of WMH load were analyzed as a function of the Cardiovascular Risk Factors, Aging and Incidence of Dementia (CAIDE) dementia risk score, as well as family history of AD and Apolipoprotein E (APOE) genotype." (PMID 30678723, 2019). "Several studies have considered the effect of APOE ε4 on mortality and although a relationship is described, it is typically explained by the presence of dementia." (PMID 29745686, 2018). "Our results are congruent with previous studies showing that the effect size of the ApoE gene on dementia was dramatically lower in over-75-year-olds." (PMID 30546303, 2018). "The association between cholesterol levels and AD risk, coupled with the functions of APOE and other genetic risk factors (e.g., SORL1), supports the role of lipid metabolism and transport in dementia." (PMID 30167451, 2018). "APOE genotype has been shown to influence age of dementia onset in the general population, and in the DS population, but genotyping is not currently used in clinical practice and we therefore did not have data on APOE status of participants." (PMID 29226868, 2018). "The presence of unfavorable alleles, e.g., in APOE cluster, TOMM40 or APOC1 is known to facilitate the dementia onset under oxidative stress." (PMID 30443289, 2018). "We further investigated the moderating effects of apolipoprotein E ε4 (APOE4) on the relationship between CA and AD-related brain changes, as CA is particularly protective in APOE4 carriers for the risk of dementia onset and Aβ accumulation." (PMID 29623037, 2018). "The characteristics of age, education, MMSE, history of stroke, hypertension, diabetes, depression, and APOE-ε4 allele carrier status were significantly different among the normal, MCI, and dementia groups." (PMID 30483213, 2018). "Using the resulting staging model, we showed that adults with a clinical diagnosis of dementia and those with APOE 3:4 or 4:4 genotype were significantly more likely to be staged later, suggesting that the model is valid." (PMID 29928657, 2018). "The percentage of APOE-ε4 carriers in AD-dementia and MCI patients was over 40%, considerably higher than we showed previously in a Portuguese control population." (PMID 29558986, 2018). "Episodic memory was investigated in 13,037 ethnically diverse elderly (ages 72 to 85 years) with two to 15 years of follow-up, and with known dementia status, age, sex, education, and APOE genotypes." (PMID 30462667, 2018). "Research has established linkages between dementia and two genes—apoliporotein E (APOE) and neuronal sortilin-related receptor (SORL1)." (PMID 30519639, 2018).
dementia (continued). "Another strength is that the APOE ε4 groups were matched for age, sex, education, presence of dementia, and overall cognitive impairment (measured by MMSE)." (PMID 30086796, 2018). "The rate of progression to dementia was significantly higher for APOE ε4 carriers or subjects with amyloid positivity." (PMID 30125290, 2018). "The effect of coding variants in dementia-causing genes on cognitive performance was tested by multiple regression analysis adjusting for gender, disease duration, age at dementia assessment, study site and APOE carrier status." (PMID 29692703, 2018). "If we accept our results as correct, despite the reduced sample size, it is possible that the participants who demonstrated a link between APOE ε4 and cognitive decline in our main analyses would in fact have gone on to develop dementia had they survived." (PMID 29745686, 2018). "The mechanism by which different APOE genotypes influence dementia development in patients with PD is still unclarified, although many studies have investigated the mechanism by which APOEε4 leads to dementia." (PMID 30405900, 2018). "Incident dementia was associated with older age, lower education, lower MMSE score, higher WHODAS II score, lower physical activity, and presence of the APOE e4 allele." (PMID 30510525, 2018). "In both Cox regression models, APOE ɛ4 continued to be an important predictor for dementia (Cox model 2: Hazard Ratio (HR) 2.85 (95% confidence interval: 1.85, 4.41), p < 0.001)." (PMID 30180830, 2018). "This tendency is reasonable since there is genetic evidence showing the apolipoprotein E (ApoE) as a common gene which links dementia, MetS, and diabetes." (PMID 29731703, 2018). "Participants with preclinical AD more frequently had a family history of dementia than subthreshold psychiatry, and they were APOE e4 carriers more frequently than the other two groups (all p < 0.01)." (PMID 30081935, 2018). "In this population-based cohort study, we seek to assess the differential associations of microvascular lesion and neurodegeneration load with cognitive decline and dementia and to examine the effect of APOE ε4 on these relationships." (PMID 30232255, 2018). "Studies suggest that APOE ε4 is associated with 3- up to 12-fold increased risk of LOAD and earlier onset of dementia in individuals with PSEN1 mutation, whereas APOE ε2 decreases the risk of LOAD." (PMID 29483867, 2018). "Lifetime (to age 80–85 y) cumulative incidence of mild cognitive impairment/dementia by baseline age and APOE-e4 dose." (PMID 28323826, 2017). "Ironically, the apoE protein itself has been shown to predict future dementia, independently of APOE genotype." (PMID 28291794, 2017). "Five-year cumulative incidence of mild cognitive impairment/dementia by baseline age and APOE-e4 dose." (PMID 28323826, 2017). "Lifetime incidence (to age 80–85 y) of MCI or dementia for the APOE-e4/e4 individuals in the long-term Framingham and Rotterdam cohorts was 34.69%–38.45% at age 60–64 y, 30.76%–40.26% at 65–69 y, and 33.3%–35.17% at 70–75 y." (PMID 28323826, 2017). "Five-year incidence of dementia was negligible except for APOE-e4/e4 individuals and those over 70 y." (PMID 28323826, 2017). "Five-year incidence of MCI/dementia was higher in the highest age stratum, particularly among APOE-e4/e4 homozygote individuals (38% in NACC and 18%–23% in Framingham and Rotterdam)." (PMID 28323826, 2017). "In 3605 participants (360 MCI, 191 dementia), an AD GRS composed of APOE + 19 LOAD GWAS variants was associated with an increased risk of incident MCI and nominally associated with amnestic and non-amnestic cases." (PMID 28259165, 2017). "This suggests that ApoE ε4 carriers have functional brain abnormalities in young adulthood, several decades before the possible onset of dementia." (PMID 28706481, 2017). "For ApoE ε4 carriers, sVEGFR2 levels were significantly decreased in patients with dementia compared to normal controls (p = 0.009; Mann-Whitney U-tests)." (PMID 29255164, 2017).
dementia (continued). "We examined whether apolipoprotein E (APOE) status interacts with vascular risk factors (VRFs) to predict the progression of white matter hyperintensities (WMHs) on brain MRI scans over a specific period of life in older age when the risk of dementia increases." (PMID 28324763, 2017). "We computed stratified cumulative incidence curves by age (60–64, 65–69, 70–75 y) and APOE-e4 dose, adjusting for the competing risk of mortality, and determined risk of MCI and/or dementia by genotype and baseline age." (PMID 28323826, 2017). "Five-year incidence of dementia alone was negligible at younger ages, even in APOE-e4/e4 homozygote individuals, but rose among older individuals, particularly among those with APOE-e4/e4 (12% in NACC and 7%–12% in Framingham and Rotterdam)." (PMID 28323826, 2017). "In the ApoE ε3/ε3 group, all patients remained cognitively stable or improved; in the ApoE ε3/ε4 group, 1 recovered from dementia, but 3 lapsed into dementia." (PMID 27677546, 2017). "Indeed, while the overall incidence of dementia increases with age, pathology becomes much more variable, the relationship between disease pathologies and cognition weakens, and the relevance of canonical risk factors for AD, including APOE genotype, decreases with advancing age." (PMID 29120328, 2017). "Confidence limits for these estimates are often wide, particularly for APOE-e4/e4 individuals and for the dementia outcome at 5 y." (PMID 28323826, 2017). "No studies explored the gene-gene, gene-environment interactions between CHRNA7 polymorphism, apolipoprotein E (APOE) ε4 status and smoking on dementia risk." (PMID 27249957, 2016). "As an example, APOE gene is recognized as a substantial factor in the majority of patients with dementia, but this biochemistry data are unavailable in the NHIRD." (PMID 27227925, 2016). "Further meta-analysis indicated an over-representation of APOE-ɛ4 carriers among PD dementia cases (n = 501) compared to PD non-dementia cases (n = 1145) [OR 1.74 (1.36–2.23)]." (PMID 27242557, 2016). "A cohort study conducted on patients with AD, patients with MCI, and healthy controls showed that the plasma level of ApoE was the lowest in those who were undergoing progress from MCI to dementia." (PMID 26682220, 2015). "In summary, we found that a cumulative genetic risk score across three genes related to cognition, brain function, and risk for dementia (BDNF, COMT, and APOE) significantly predicted late-life cognitive impairment." (PMID 26366299, 2015). "This would suggest that biological and/or environmental components moderate the APOE ε4 effect in this population, resulting in greater volume loss in AD-specific brain regions, which could result in higher risk to Chinese ε4 carriers of developing dementia later in life." (PMID 25738563, 2015). "We have also established novel methods to express apoE isoforms in mouse brain to study apoE-related pathways in AD and related dementia." (PMID 25871773, 2015). "Several previous studies have also reported that the prevalence of the APOE ε4 allele was higher among patients with MCI, AD and other types of dementia compared with the general population." (PMID 24914687, 2014). "The AD-GRS including APOE had larger relative effects on dementia in NHW than in NHB, although absolute effects were similar." (PMID 25328845, 2014). "The effect of gene-gene interaction on dementia was reported by a study that aimed to compare the age- and gender-specific distribution of the APOE and alpha-1-antichymotrypsin (ACT) genes and the effect of this interaction on AD." (PMID 25177512, 2014). "The effect of APOE genotype on dementia incidenceappeared to be principally confined to the youngest age group." (PMID 29213926, 2014). "We found some evidence that the AD-GRS excluding APOE is more predictive of dementia among NHB males compared to NHB females." (PMID 25328845, 2014).
dementia (continued). "The link of APOE ε4 to dementia in CTE is unexpected on the basis of tauopathy, since APOE ε4 modulates Aβ pathology in AD but not tauopathy." (PMID 25231386, 2014). "We found a strong association between APOE genotype and the prevalence of both 10/66and DSM-IV dementia, with effect sizes very similar to those reported in othersettings." (PMID 29213926, 2014). "In the pooled model using the alternative AD-GRS excluding APOE, the AD-GRS was associated with an OR of 1.46 (95% CI: 1.11, 1.93; P = 0.008) for dementia risk." (PMID 25328845, 2014). "The study showedthat the relationship between APOE ε4 and incident dementia isstronger in the younger-old than the older-old and that this change must betaken into account in models of dementia." (PMID 29213926, 2014). "The distribution of BuChE K and APOE genotypes in the study population of 52 patients with cognitive impairment (AD, n=28; other dementias, n=12; SMCI, n=12) and 17 healthy matched controls." (PMID 24312390, 2013). "There is a strong genetic link to some forms of dementia, including the presence of the APOE-e4 variant of the Apolipoprotein E gene." (PMID 22998923, 2012). "The only study that carried out APOE genotyping reported higher prevalence of dementia in people with APOEε4." (PMID 23289076, 2012). "The size of atheroma plaques in the abdominal and thoracic aorta of patients with dementia and/or dyslipidemia is significantly larger in APOE-4 carriers than in APOE-3 carriers." (PMID 22482072, 2012). "In over 100 clinical trials for dementia, APOE has been used as the only gene of reference for the pharmacogenomics of AD." (PMID 22482072, 2012). "The volunteers are highly motivated and highly educated, and the frequency of both family history of dementia and APOE-4 is higher than what would be observed in the general population." (PMID 22536535, 2012). "Over 500 studies reported during the past two decades have postulated the potential involvement of APOE in dementia and other CNS disorders." (PMID 22482072, 2012). "After further standardizing or adjusting for the compositional differences in APOE genotype, dementia prevalence among both 'black' and 'mixed' groups was slightly lower than among those identified as 'white'." (PMID 21435264, 2011). "APOE genotype was determined in 2520 participants, and genetic admixture in 235 dementia cases and 349 controls." (PMID 21435264, 2011). "We examined the effect of APOE genotype on dementia prevalence using APOE e3/e3 genotypes as the reference category." (PMID 21435264, 2011). "After adjusting for age, sex and education, APOE e3/e4 (PR = 2.59, 95%CI 2.04-3.28) and APOE e4/e4 genotypes (PR 2.88, 95% CI1.58-5.27) were strongly associated with dementia." (PMID 21435264, 2011). "Potential moderating variables at baseline are: socio-demographic characteristics, body mass index, subtype of dementia, apolipoprotein E (ApoE) genotype, medication use and comorbidities." (PMID 21827648, 2011). "In this study we investigated the associations between hypertension, diabetes, heart disease, stroke, APOE ε4 and dementia." (PMID 20576093, 2010). "Indeed, adverse health behaviors are risk factors for impaired cognition and dementia; however, a recent review concluded that more research is needed to confirm or refute the hypothesis of a differential effect of health behaviors among APOE ε4 carriers." (PMID 20515477, 2010). "We aimed to assess the relation between vascular health, diabetes, APOE and dementia using data from the Aging, Demographics, and Memory Study (ADAMS)." (PMID 20576093, 2010). "The relation of hypertension, diabetes, heart disease, stroke, medication usage, and APOE ε4 to dementia was modelled using adjusted multivariable logistic regression." (PMID 20576093, 2010). "Treated stroke (odds ratio [OR] 3.8, 95% confidence interval [CI] 2.0, 7.2), untreated stroke (OR 3.5, 95% CI 1.7, 7.3), and APOE ε4 (OR 2.8, 95% CI 1.7, 4.5) all increased the odds of dementia." (PMID 20576093, 2010).
dementia (continued). "Seventy four of the 94 participants in the study had first degree relatives with AD, resulting in a sample likely to be sensitive to early effects of APOE, and also likely to include a number of individuals prodromal for dementia." (PMID 18620605, 2008). "Peila evaluated the association of diabetes alone or combined with the apolipoprotein E (ApoE) gene with incident dementia in a population-based cohort of 2,574 Japanese-American men." (PMID 21876656, 2008). "Without strong underlying risks from APOE ε3 and ε4, almost all AD and half of all dementia would not occur." (PMID 41522467, 2026). "The strongest genetic risk factor for dementia-APOE genotype-has not been assessed in population-scale cohorts of South Asian ancestry." (PMID 42205162, 2026). "We identified specific independent mass spectrometry signals which may be candidate biomarkers of cognitive function, APOE ε4 status, and could aid in the early detection of dementia; however, further replication studies in other populations are required." (PMID 41646675, 2026). "Intervening on APOE should be prioritised to facilitate dementia prevention." (PMID 41522467, 2026). "A better understanding of sex-specific associations, interaction, and joint effects of vascular and APOE ε4 status on cognitive decline and dementia may provide critical insight for targeted prevention." (PMID 41536502, 2026). "P values for APOE interaction were .004 for cognition and .10 for dementia." (PMID 41854609, 2026). "In stratified analyses, the association between eGDR and dementia was stronger in females versus males and in APOE ɛ4 noncarriers versus carriers." (PMID 41181882, 2026). "Frailty is an important predictor of future cognitive decline in cognitively unimpaired people, as increased frailty severity increases the risk of MCI/dementia, independent of APOE ε4 carrier status." (PMID 41569280, 2026). "The overall associations of blood pressure metrics and APOE ε4 allele with dementia risk in the non-imputed sample were consistent with those observed in the imputed analysis." (PMID 41536502, 2026). "A higher ratio of processed to total meat was unfavorably associated with dementia (sHR, 1.14; 95% CI, 1.01 to 1.29; P = .04), showing no APOE interaction and no substantial difference between unprocessed red meat and poultry." (PMID 41854609, 2026). "Specific mechanisms connecting APOE ε4 with cardiometabolic dysfunction and dementia, however, remain unclear." (PMID 39364911, 2025). "Furthermore, we observed a significant interaction between travel mode and APOE ε4 status for all-cause dementia and LOD, prompting the gene-environment interaction in dementia occurrence." (PMID 40489111, 2025). "The results from our study support the notion that there may be an interplay between APOE ε4 status and diet in relation to AD and dementia." (PMID 40222839, 2025). "Several studies in the Colombian kindred suggested that carriers of the APOE ε4 allele developed earlier dementia onset compared to non-carriers." (PMID 40103931, 2025). "We used Bayesian reanalysis with an independent t‐statistic to determine evidence for or against an effect of antibody treatment on Clinical Dementia Rating scale Sum of Boxes (CDR‐SB) in ApoE ε4 homozygotes, and a Bayesian random‐effect meta‐analysis to determine the effect size." (PMID 40225236, 2025). "Ethnicity did not significantly impact dementia risk factors, despite differences in APOE allele frequencies." (PMID 40904564, 2025). "Among the most consistently replicated GWAS loci for ADRD is the APOE genotype which is a strong predictor of dementia liability, currently explaining more phenotypic variability than polygenic scores constructed from hundreds of small-effect loci derived from GWAS." (PMID 40568661, 2025).